GMDS (GDP-mannose 4,6-dehydratase)
Description:
Catalyzes the conversion of GDP-D-mannose to GDP-4-dehydro-6-deoxy-D-mannose.
Synonyms: GMD; SDR3E1
Tractability: Small molecule: a structure with a bound ligand is known; it has a high-quality binding pocket. PROTAC: ubiquitination databases record sites on it; its protein half-life has been measured.
Target class: Enzyme; Lyase
Gene: Protein-coding gene on chromosome 6 (1,623,793 to 2,245,702, reverse strand). Ensembl gene ENSG00000112699.
Pathways (Reactome):
Metabolism of proteins: GDP-fucose biosynthesis
Gene Ontology:
Molecular function: GDP-mannose 4,6-dehydratase activity; identical protein binding; NADP+ binding; protein binding
Biological process: 'de novo' GDP-L-fucose biosynthetic process; GDP-mannose metabolic process; GDP-L-fucose biosynthetic process; Notch signaling pathway
Cellular component: extracellular exosome; cytoplasm; cytosol
Genetic constraint (gnomAD): Loss-of-function variants: 6 observed, 16.47 expected, observed/expected ratio (o/e) 0.36, 90% interval 0.2 to 0.72. The upper end of that interval is the gene's LOEUF score, 0.72, which puts it in group 2 of 6, group 1 being the genes least tolerant of losing a copy. Missense variants: 172 observed, 190.82 expected, observed/expected ratio (o/e) 0.9, 90% interval 0.8 to 1.02. Synonymous variants: 90 observed, 82.72 expected, observed/expected ratio (o/e) 1.09, 90% interval 0.92 to 1.3.
Homologues: Orthologues: chimpanzee GMDS (100% identical), macaque GMDS (99% identical), mouse Gmds (97% identical), rat Gmds (97% identical), guinea pig GMDS (91% identical), rabbit GMDS (86% identical), tropical clawed frog gmds (84% identical), zebrafish gmds (83% identical), dog GMDS (81% identical), pig GMDS (81% identical), Drosophila melanogaster Gmd (67% identical), Caenorhabditis elegans bre-1 (64% identical), and 1 more. Paralogues in human: UXS1 (19% identical), HSD3B2 (18% identical), HSD3B1 (18% identical), SDR42E2 (17% identical), GALE (17% identical), SDR42E1 (17% identical), NSDHL (16% identical), HSD3B7 (16% identical), TGDS (14% identical), GFUS (12% identical).
Diseases named in the same sentence as GMDS in open-access papers:
GMDS is named in the same sentence as 33 diseases in open-access papers, as found by Europe PMC text mining. Sharing a sentence is not in itself a finding about the gene and the disease. The quoted sentences say what the papers report.
colon cancer (12 papers, 2012 to 2025). "Colon cancer cells HCT116 have a mutation of GDP-mannose-4,6-dehydratase (GMD), an enzyme required for the biosynthesis of GDP-Fuc, the essential donor substrate for Fuc-transferases." (PMID 34069424, 2021). "GMDS mutations have been shown to be positively related to colorectal cancer metastasis, and GMDS deficiency accounts for tumor escape and resistance to cellular apoptosis in colon cancer cells." (PMID 29843634, 2018). "Further analysis with more number of samples will be required to determine the correlation between GMDS mutation and colon cancer progression." (PMID 23922970, 2013). "Mutations of GMDS found in colon cancer cells induced a malignant phenotype, leading to rapid growth in athymic mice resistant to natural killer cells." (PMID 24970126, 2012). "GMDS deficiency in colon cancer cells leads to resistance to TRAIL-induced apoptosis by inhibiting the transition from a primary death-inducing signaling complex (DISC) to a secondary complex II, thereby inducing tumor development and evading natural killer cell-mediated tumor immune surveillance." (PMID 40821120, 2025). "Also, an in vitro study found that GMDS deficiency in colon cancer cells made them resistant to receptor-mediated apoptosis." (PMID 31337362, 2019). "Interestingly, mutations in the GMDS gene have been identified in metastatic lesions of some colon cancers (10%)." (PMID 30909444, 2019). "Deletion mutation of the GMDS gene plays a pivotal role in fucosylation in human colon cancer." (PMID 24255851, 2013). "For example, 6,6-difluoro-l-fucose and 6,6,6-trifluoro-l-fucose displayed potent inhibitory effects against colon cancer cells in vitro, and the authors suggested that the most likely target is GMDS." (PMID 40821120, 2025). "Some human colon cancer cells, such as HCT-116, have mutations in GMDS (the gene encoding the enzyme GDP-mannose-4,6-dehydratase, which is crucial for the synthesis of the nucleotide sugar donor GDP-fuc via the de novo pathway)." (PMID 26539643, 2016). "Previously, we found complete loss of fucosylation in the colon cancer cell line HCT116 due to a mutation in the GDP-fucose synthetic enzyme, GDP-mannose-4,6-dehydratase (GMDS)." (PMID 23922970, 2013). "To answer this question, we transplanted a colon cancer cell line, HCT 116 which lacks fucosylation due to GMDS mutation, into athymic mice and investigated serum levels of Fuc-Hpt during tumor development." (PMID 24970126, 2012). "Research has shown that mutations in the GDP-mannose-4,6-dehydratase (GMDS) gene, essential for fucosylation, result in resistance to TRAIL-induced apoptosis and subsequent evasion from NK cell-mediated surveillance in human colon cancer." (PMID 39119332, 2024). "We provided confidential evidence that GMDS might serve as a tumor-promoting factor in lung adenocarcinoma, which is in contrast to the reported anti-tumor functions in colon cancers." (PMID 29843634, 2018). "Also the colon cancer cell line HCT116 bears a GMDS mutation, resulting in almost complete absence of fucosylation." (PMID 30909444, 2019).
colorectal cancer (5 papers, 2013 to 2025). A primary or metastatic malignant neoplasm that affects the colon or rectum. "Several mutations in GMDS have been identified in tissue samples from patients with colorectal cancer." (PMID 40642090, 2025). "GDP-mannose-4,6-dehydratase (GMDS) has been shown to have exon deletions linked to progression of colorectal cancer." (PMID 31337362, 2019). "In conclusion, the present study demonstrated that GMDS mutation should be involved in the progression of colorectal cancer." (PMID 23922970, 2013). "If loss of fucosylation is critical for tumor metastasis during colorectal cancer progression, the frequency of GMDS mutation would likely be increased in metastatic lesions." (PMID 23922970, 2013). "In the present study, we investigated the frequency of GMDS mutation in a number of clinical colorectal cancer tissue samples: 81 samples of primary colorectal cancer tissue and 39 samples of metastatic lesion including liver and lymph node." (PMID 23922970, 2013). "In previous our study, the GMDS mutation was identified by gDNA sequencing in two out of 100 cases of human colorectal cancer tissue and by RT-PCR analysis in five out of 10 cases of microdissected human ovarian cancer tissue." (PMID 23922970, 2013). "The GMDS mutations in the metastatic lesions were consistent with those from the original colorectal cancer tissues." (PMID 23922970, 2013). "Next-generation DNA sequence analysis may give us more information about GMDS mutation in colorectal cancer." (PMID 23922970, 2013). "Frequency of GMDS mutation in original and metastatic lesions of human colorectal cancer." (PMID 23922970, 2013). "A deficiency in GDP-mannose-4,6-dehydratase (GMDS), a GDP-mannose converting enzymes essential for de novo fucosylation in colorectal cancer cells, was found to confer resistance to TRAIL." (PMID 29498673, 2018). "As a critical enzyme in fucosylation, GMDS deregulation was also detected in colorectal cancer and GMDS dysfunction led to tumor escape and resistance to cellular apoptosis in colorectal cancer cells." (PMID 29843634, 2018). "Twenty-eight colorectal cancer tissues without GMDS mutation showed positive staining for both GMDS and AAL." (PMID 23922970, 2013).
glaucoma (3 papers, 2015 to 2024). Increased pressure in the eyeball due to obstruction of the outflow of aqueous humor. "To date, the response to latanoprost of patients with glaucoma and ocular hypertension, is reported to be associated with the genetic polymorphism of seven genes (ABCB1, SLCO2A1, AFAP1, GMDS, PTGS1, MRP4, and PTGFR)." (PMID 36313286, 2022). "Rs1045642 in ABCB1, rs4241366 in SLCO2A1, rs9503012 in GMDS, rs10306114 in PTGS1, rs11568658 in MRP4, rs10786455 and rs6686438 in PTGFR were reported to be positive with the response to prostaglandin analogs in patients with glaucoma." (PMID 36313286, 2022).
lung adenocarcinoma (3 papers, 2018 to 2025). A carcinoma that arises from the lung and is characterized by the presence of malignant glandular epithelial cells. "Taken together, this study provided valuable insights into the molecular mechanisms underlying GMDS-regulated cell growth in lung adenocarcinoma." (PMID 29843634, 2018). "Nude mice were transplanted with lung adenocarcinoma H1299 cells, and cell groups were either infected with scrambled-shRNA or GMDS-shRNA lentivirus particles." (PMID 40725456, 2025). "GMDS expression is significantly upregulated in lung adenocarcinoma at both mRNA and protein levels." (PMID 29843634, 2018). "We further examined GMDS protein density using tissue microarray in paired human lung adenocarcinoma samples and confirmed the upregulation of GMDS in human lung adenocarcinoma." (PMID 29843634, 2018). "Here we established xenograft mice model of lung adenocarcinoma with subcutaneously injection of H1299 cells infected with lentivirus expressing either Scr-shRNA or GMDS-shRNA into nude mice." (PMID 29843634, 2018). "GMDS upregulation was further confirmed in specimens from lung adenocarcinoma patients using immunohistochemistry." (PMID 29843634, 2018). "Here we focused on GMDS, a gene involved in glycosylation, and confirmed its tumor-promoting role in lung adenocarcinoma in vitro and in vivo." (PMID 29843634, 2018). "Taken together, these results confirmed that GMDS is involved in tumorigenesis of lung adenocarcinoma." (PMID 29843634, 2018). "Colony formation assay was used here to examine the impact of GMDS knockdown on colony formation ability in human lung adenocarcinoma cells A549 and H1299." (PMID 29843634, 2018). "Our studies in two human lung adenocarcinoma cells A549 and H1299 cells confirmed that GMDS was important for tumorigenesis of lung adenocarcinoma in vitro." (PMID 29843634, 2018). "Two human lung adenocarcinoma cell lines A549 and H1299 were infected with lentivirus expressing either Scr-shRNA or GMDS-shRNA to investigate the impact of GMDS on cell growth of lung adenocarcinoma." (PMID 29843634, 2018). "Transcriptome changes with GMDS knockdown in lung adenocarcinoma cells were also examined to provide insights into related molecular mechanisms." (PMID 29843634, 2018). "GMDS upregulation in lung adenocarcinoma implies a potential biomarker and targets for lung adenocarcinoma diagnosis and treatment." (PMID 29843634, 2018). "It was shown that GMDS expression at mRNA level was significantly upregulated in lung adenocarcinoma tissues as compared to adjacent normal tissues." (PMID 29843634, 2018). "Evasion of apoptosis is another hallmark of cancer, and would also promote cell growth and proliferation, so it is important to examine the cell apoptotic status in human lung adenocarcinoma cells infected with lentivirus expressing GMDS-shRNA." (PMID 29843634, 2018). "Lentivirus-mediated shRNA strategy inhibited GMDS expression efficiently in human lung adenocarcinoma cells A549 and H1299, and GMDS knockdown impaired cell proliferation, colony formation ability, induced cell cycle arrest, and apoptosis in both cell lines." (PMID 29843634, 2018). "Then, two lung adenocarcinoma cell lines A549 and H1299 cells were chosen for further functional analysis of GMDS." (PMID 29843634, 2018). "Additionally, up-regulation of GMDS mRNA and protein has been shown in lung adenocarcinoma compared to surrounding normal tissue." (PMID 40725456, 2025). "In addition, GMDS protein expression in common lung adenocarcinoma cell lines A549, H1299 and SPC-A-1 was examined." (PMID 29843634, 2018). "Here we examined GMDS expression level at both mRNA and protein level in lung adenocarcinoma." (PMID 29843634, 2018). "It is possible that GMDS might be involved in the early stage of lung adenocarcinoma development, so the impact of GMDS expression on cell proliferation and survival in lung adenocarcinoma was examined in the following studies." (PMID 29843634, 2018).
lung adenocarcinoma (continued). "The impact of GMDS knockdown on lung adenocarcinoma in vitro and in vivo was investigated." (PMID 29843634, 2018). "Furthermore, GMDS knockdown inhibited tumorigenesis in a xenograft mice model of lung adenocarcinoma." (PMID 29843634, 2018). "Both confirmed that CDKN1A was the core of GMDS-mediated lung adenocarcinoma progression." (PMID 29843634, 2018). "Taken together, our study revealed that GMDS was upregulated in lung adenocarcinoma tissues, which might serve as a biomarker for lung adenocarcinoma." (PMID 29843634, 2018). "However, in vivo evidence for the involvement of GMDS in tumorigenesis of lung adenocarcinoma remained elusive." (PMID 29843634, 2018). "Human lung adenocarcinoma cell lines A549 and H1299 were infected with lentivirus expressing either Scr-shRNA or GMDS-shRNA and cell cycle distribution was analyzed using propidium iodide (PI) staining in combined with fluorescence-activated cell sorting (FACS)." (PMID 29843634, 2018). "Furthermore, IPA network analysis showed that CASP8-CDKN1A axis was at the core of GMDS-associated gene interaction network, emphasizing the core of CDKN1A in GMDS-mediated lung adenocarcinoma growth." (PMID 29843634, 2018). "As unlimited cell proliferation ability was the key feature of tumor initiation and development, we further determined the influence of GMDS knockdown on cell proliferation ability in both lung adenocarcinoma cell lines A549 and H1299 with MTT assay for continuous 5 days." (PMID 29843634, 2018). "Lentiviral–mediated short hairpin RNA (shRNA) specifically targeting human GMDS was employed to inhibit GMDS expression in lung adenocarcinoma cells, and knockdown efficiency was confirmed at both mRNA and protein level by quantitative real-time polymerase chain reaction (qPCR) and western blot." (PMID 29843634, 2018). "What’s more, roles of GMDS in lung adenocarcinoma have not been described previously, so according to our knowledge, this study was the first to systematically analyze the functional impact and molecular mechanisms of GMDS in lung adenocarcinoma in vitro and in vivo." (PMID 29843634, 2018). "Here, we first analyzed gene expression profiling in 57 paired lung adenocarcinoma cases from The Cancer Genome Atlas (TCGA) database and found that GMDS expression was significantly upregulated in lung adenocarcinoma tissues as compared to adjacent normal tissues." (PMID 29843634, 2018). "We first examined GMDS expression at mRNA level in human lung adenocarcinoma using transcriptome data of 57 paired human lung adenocarcinoma tissues from TCGA database and showed that GMDS was upregulated in human lung adenocarcinoma as compared to adjacent normal tissue." (PMID 29843634, 2018). "Microarray analysis explored the GMDS-mediated molecular network and revealed that the CASP8-CDKN1A axis might be critical for lung adenocarcinoma development." (PMID 29843634, 2018). "We then examined the correlation between GMDS expression at mRNA level and prognosis in one patient cohort (using data set GSE31210), and revealed that higher GMDS expression was correlated with poor prognosis of lung adenocarcinoma patients." (PMID 29843634, 2018).
gastric cancer (2 papers, 2021 to 2022). A primary or metastatic malignant neoplasm involving the stomach. "Among the gastric cancer patients, all the 15 overlapping genes appear to be isolated from each other, whereas among the controls, three gene pairs (SPINT1 and GMDS, GMDS and TNRC18, and CSNK1D and RNF19B) are connected." (PMID 33596182, 2021).
Intellectual disability (2 papers, 2016 to 2017). "In one key study, the severity of mental retardation in patients was found to be strongly associated with the size and position of FOXC1 deletions and whether they extended further to encompass exons of the nearby GMDS gene." (PMID 27103944, 2016).
liver cancer (2 papers, 2013 to 2024). An epithelial or non-epithelial malignant neoplasm that arises from the liver. "Although most of the GMDS mutations observed in this study were heterozygous, homozygous deletion mutation was observed in one metastatic liver cancer tissue (case 1)." (PMID 23922970, 2013).
ovarian carcinoma (2 papers, 2013 to 2024). A malignant neoplasm originating from the surface ovarian epithelium. "GMDS mutation has been observed in colon (HCT116, LS174T, NCI-H716) and gastric (SCH) cancer cell lines as well as in human colon and ovarian cancer tissues." (PMID 23922970, 2013).
congenital glaucoma (1 paper, 2024). "In the gene knockout groups with genes related to congenital glaucoma, GMDS, FOXC1, LTBP2, TEK, and CYP1B1, no distinct patterns were observed in the transcriptome of these gene knockout groups." (PMID 38272457, 2024).
Dandy-Walker syndrome (1 paper, 2016). "Specifically, it is unknown what role non-coding mutations around the FOXC1/GMDS locus might play in developmental disorders such as Dandy-Walker syndrome." (PMID 26382291, 2016).
meningioma (1 paper, 2025). A generally slow growing tumor attached to the dura mater. "GMDS converts GDP-d-mannose to GDP-4-keto-6-deoxymannose and has been linked to higher-grade meningiomas through integrative transcriptomic and proteomic studies." (PMID 40562609, 2025).
metastatic colorectal cancer (1 paper, 2013). "In this study, we further demonstrated the GMDS mutation in several human original and metastatic colorectal cancer tissues." (PMID 23922970, 2013). "In this study, we investigated the frequency of GMDS mutation in metastatic colorectal cancer tissues such as liver and lymph node." (PMID 23922970, 2013).
Obesity (1 paper, 2025). Accumulation of substantial excess body fat. "Our analysis suggested significant enrichment (corrected P‐value < 0.01) in various catalogs, including obesity‐related traits (e.g., GMDS, PRKG1, and BMP2), Height (e.g., IGF2BP3, BMP2, and BMP3), and Body mass index (e.g., BMP2)." (PMID 40167159, 2025).
primary open-angle glaucoma (1 paper, 2025). "SNPs near the GMDS gene are also associated with primary open-angle glaucoma and may potentially affect treatment efficacy with latanoprost, a common drug for reducing the intraocular pressure." (PMID 40725456, 2025).